RNU2-70P (RNA, U2 small nuclear 70, pseudogene)
Gene: Small nuclear RNA gene on chromosome 1 (236,267,780 to 236,267,958, forward strand). Ensembl gene ENSG00000222650.
Homologues: Orthologues: chimpanzee U2 (98% identical), rat LOC120096841 (80% identical), guinea pig U2 (75% identical), tropical clawed frog U2 (54% identical). Paralogues in human: U2 (92% identical), RNU2-6P (88% identical), U2 (86% identical), RNU2-26P (85% identical), RNU2-2 (84% identical), RNU2-57P (84% identical), RNU2-4P (83% identical), RNU2-59P (82% identical), RNU2-68P (81% identical), RNU2-3P (80% identical), RNU2-48P (80% identical), RNU2-14P (80% identical), and 66 more.